HIF1A (hypoxia inducible factor 1 subunit alpha)
Diseases named in the same sentence as HIF1A in open-access papers (continued):
Sharing a sentence is not in itself a finding about the gene and the disease.
tumor (continued). "Quantitation of YAP1 interaction with HIF1α (red foci) clearly showed an increase in this interaction in RCC tumor tissues, where distribution of YAP1 was more nuclear than cytoplasmic." (PMID 35937460, 2022). "During tumor growth, hypoxic zones are formed in the tumor mass, where HIF-1α can stimulate VEGF protein increase." (PMID 36014335, 2022). "Tumor cell adaptions to hypoxia are primarily mediated by hypoxia-inducible factor-1 alpha (HIF-1α)." (PMID 35795658, 2022). "Under hypoxic conditions, suppression of HIF-1α expression can lead to changes in tumor cell proliferation, invasion, metastasis, and apoptosis." (PMID 35396948, 2022). "At present, there are several methods to improve the oxygen in tumor microenvironment include hyperbaric oxygen therapy, HIF-1α pathway inhibitor and inducing tumor vessel normalization." (PMID 36531323, 2022). "Tumor-associated macrophage (TAM)-induced peritoneal mesothelial cell fibrosis, CCL22/CCXR4 axis, and HIF-1α have been reported to facilitate tumor cell invasion." (PMID 35740397, 2022). "HIF-1α regulates a broad range of genes involved in epithelial to mesenchymal transition, disrupting basement membrane of surrounding tumor tissue and invasion." (PMID 36014432, 2022). "In 2017, researchers showed that knocking out HIF1α in tumor-infiltrating T cells increases peroxisome proliferator-activated receptor-α (PPAR-α) expression in these cells, a transcription factor which promotes fatty acid catabolism." (PMID 35414042, 2022). "HE staining revealed many areas of necrosis in tumours exposed to wortmannin and/or 12 Gy irradiation, as well as in Glut‐1 and/or HIF‐1α knockout tumours." (PMID 35415942, 2022). "In the human non-small cell lung cancer cell line A549, it was found that silencing HIF-1α expression reduced glutamine consumption in the tumor cells." (PMID 35897036, 2022). "A2AR blockade reduces CD4+ FOXP3+ Tregs infiltration and enhances the anti-tumor response of CD8+ T cells by attenuating hypoxic HIF-1α signaling." (PMID 36532071, 2022). "Here, HIF-1α mediates the shift in glucose metabolism from oxidative phosphorylation to glycolysis in tumor cells." (PMID 36140753, 2022). "Incomplete ablation promoted angiogenesis through HIF-1α/VEGF signal pathway leading to tumor invasion and metastasis." (PMID 36081558, 2022). "Pearson correlation analysis showed that there was a significant positive correlation between hypoxia score and the expression of HIF-1α, the main molecular mediator of hypoxia adaptation in tumor cells, with correlation coefficient R = 0.313." (PMID 36338972, 2022). "HIF-1α is a transcription factor and an oncoprotein that can increase tumor cells mobility and metastasis." (PMID 35527284, 2022). "Decreased HIF1A activity hampers the immune-evasive programme and enhances tumour recognition by T-cells." (PMID 35106125, 2022). "Overall, RC@TFC NPs were able to accumulate into the tumor, mitigate hypoxia, and downregulate HIF-1α, contributing to considerably increased therapeutic effects of PDT." (PMID 36145513, 2022). "HIF1α suppresses oxidative phosphorylation and stimulates glycolysis (the Warburg effect) in most of the tumor, except for one cancer subpopulation, which was capable of using both metabolic modalities." (PMID 35193955, 2022). "To further examine the clinical implication of METTL4 and 6mA, we measured the 6mA levels in upper tract urothelial cancer (UTUC) patient samples since HIF-1α contributes to tumor progression in UTUC patients." (PMID 36461076, 2022). "In an overexpressed SOCS5 orthotopic HCC model, we showed that LHAVL-induced HIF-1α expression promotes HCC tumor metastasis and, more importantly, that HCC tumors overexpressing SOCS5 undergo LHAVL, with a significant rise in metastatic ability." (PMID 36319626, 2022).
tumor (continued). "Hypoxia-inducible factor (HIF) is upregulated in the tumor hypoxia microenvironment, in which HIF-1α and HIF-2α are considered as the main response regulators." (PMID 36439690, 2022). "Blockage of Nrf2 can inhibit tumor growth by reducing the expression level of some genes involved in cell growth like HIF-1a, VEGF, PDGF, angiopoietin, and angiogenin." (PMID 35906617, 2022). "Both ABCB1 and HIF1A are upregulated under hypoxic conditions, suggesting that HIF1A is related to tumor radiotherapy and chemotherapy resistance mechanisms." (PMID 35659268, 2022). "HIF-1α has been shown to be necessary for the tumor-promoting effects of CAFs in NSCLC, and ROS are important signaling molecules that sustain, in part, the metabolic symbiosis between CAFs and carcinoma cells." (PMID 35814364, 2022). "NRF2 increases tumor growth via heightened angiogenic and hypoxic response through the production of HIF1α and VEGFA after transforming MSCs to CSCs." (PMID 36213236, 2022). "HIF-1α promotes malignant characteristics and helps transfer tumor cells to distant organs with the subsequent expression of migrating genes and TGFs." (PMID 35592530, 2022). "After entering the nucleus, HIF-1α regulates the expression of more than 300 proteins and has a profound effect on tumor metabolism, proliferation, migration, and cell death." (PMID 36038533, 2022). "Subsequent tumor revascularization occurs via hypoxia-inducible factor 1α (HIF1α)-dependent and HIF1α-independent recruitment of bone marrow-derived cells (BMDCs)." (PMID 36675979, 2022). "Consistent with the previous data 8, we found that hypoxia, TGF-β1 and tumor CM induced the upregulation of HIF-1α in fibroblasts and the HIF-1α high-expressed fibroblasts was considered as the CAFs." (PMID 36439884, 2022). "Hypoxia-inducible factor 1 (HIF1) as a heterodimeric transcription factor composed of HIF1α and HIF1β subunits, is also regarded as a major angiogenetic regulator in the tumour microenvironment." (PMID 35440045, 2022). "Hypoxia-inducible factor-1α (HIF-1α) is one of the key mediators of angiogenesis and survival in tumor metastasis that has been established as an important cancer drug target." (PMID 36558113, 2022). "In the microenvironment in which tumor cells are located, the enhanced glycolytic uptake by tumor cells is highly dependent on the NF-κB/HIF-1α hypoxic pathway." (PMID 35178457, 2022). "High activity of HIF-1α in tumor microenvironment down-regulated infiltration and activity of CD8+ T cells." (PMID 36761171, 2022). "During these processes, tumor cells under hypoxic conditions induce the activation of hypoxia inducible factor-1α (HIF-1α) that is a key responder adapted to intratumoral hypoxia." (PMID 34969360, 2022). "This highlights the centrality of HIF-1α and c-Myc in the metabolic landscape of the tumor cells and their progression." (PMID 36618350, 2022). "Reduced SLC2A1, ABCB1, MMP2, twist family bHLH transcription factor 1, and VEGFA expression in tumor cells; downregulation of HIF-1α." (PMID 35640930, 2022). "Conversely, the combination of emodin and cisplatin downregulated the multidrug resistance-1 gene and HIF-1α production in lung tumor cells, which restricted cancer cell proliferation, adhesion, migration, and tumor angiogenesis." (PMID 36338690, 2022). "The loss of FBP1 binding mediated by HAND2-AS1 leads to a decrease in HIF1α translation, which attenuates glycolysis and further reduces tumor growth." (PMID 35625948, 2022). "This indicates efficient tumor oxygenation and hypoxia relief by the hMVs, which was also confirmed by immunofluorescence staining of HIF-1α in tumor sections after 24 h post-injection." (PMID 35624636, 2022). "Tumor formation creates a hypoxic microenvironment that activates hypoxia-inducible factor 1α (HIF1α) and nuclear transcription factor-κB, ultimately triggering vascular endothelial growth factor A (VEGF-A) secretion and the subsequent angiogenesis." (PMID 36092163, 2022).
tumor (continued). "HIF-1α has been identified as an important transcription factor involved in tumorigenesis and tumor development by regulating the expression of genes related to angiogenesis, tumor metastasis, cell proliferation, and chemoradiotherapy resistance." (PMID 35795276, 2022). "HIF-1α also activates several oncogenic growth factors, thereby stimulating tumor metastasis to more oxygenated regions." (PMID 36140753, 2022). "In tumor progression, up-regulation of HIF-1α plays a vital role in CSC-regulated cancer hallmarks by controlling different gene expressions involved in CSC maintenance." (PMID 36014432, 2022). "Positive HIF-1α IHC expression significantly correlated with greater tumor size, higher histological grade, positive lymph node status, and higher tumor TNM stage as well as poorer postoperative survival." (PMID 36012111, 2022). "In preclinical studies, inhibition of HIF-1α activity by various methods and down-regulation of various HIF-1α-mediated gene expressions have shown a significant impact on tumor growth." (PMID 35684364, 2022). "Under hypoxia, HIF-1α transcriptionally regulates a battery of genes that are pivotal for tumor angiogenesis and metastasis, including the VEGFs." (PMID 36296726, 2022). "Elevated HIF-1α expression was also positively associated with four clinicopathological characteristics, namely LNM, DM, tumor size, and clinical stage of tumor." (PMID 35845307, 2022). "The lncRNA HITT directs EZH2 to promoter of HIF-1α to form RNA–DNA triplex, leading to HIF-1α down-regulation and subsequent tumor suppression." (PMID 35236381, 2022). "In other studies, in head and neck squamous carcinoma, the HIF-1α–MIF axis contributed to the recruitment of myeloid (CD11b+-Gr-1+) cells to enhance tumor growth and angiogenesis." (PMID 36496973, 2022). "Since high levels of HIF-1α are strongly correlated with the expression of survivin, a protein involved in tumor progression, we analyzed the transcript levels of the corresponding gene Baculoviral IAP Repeat-Containing Protein 5 (BIRC5)." (PMID 36142158, 2022). "As mentioned, HIF-1α is part of the adaptive response of tumor cells to hypoxia, as it activates up to 200 genes crucial for tumor proliferation and metastasis." (PMID 36140753, 2022). "HIF-1α is closely related to the growth, invasion, and metastasis of tumor tissues, and it is also a transcriptional regulator that plays an important role in tumor hypoxia." (PMID 35693265, 2022). "The mechanisms of lactate’s influence on carcinogenesis induction and tumors progression suggest the activation of the “hyaluronic system” in tumor-associated fibroblasts and the stimulation of VEGF and HIF-1α." (PMID 36230479, 2022). "HIF-1α inhibitors can activate the anti-tumor functions of NK cells by elevating interferon-γ (IFN-γ) production." (PMID 36686483, 2022). "HIF2α-immunopositive cells, either HIF2αNUC or HIF2αCYT, were homogeneously distributed throughout the whole tumor tissue, contrasting with the focal and patchy accumulation of HIF1α protein described in PPGL and most other types of cancers." (PMID 35740651, 2022). "S100B is activated by hypoxia via HIF-1a dependent manner to promoter cell proliferation, invasion and metastasis under tumor hypoxic conditions." (PMID 35368338, 2022). "After TACE, the microenvironment for a tumor is hypoxic and HIF1-α is upregulated, thereby causing the upregulation of VEGF and inducing tumor angiogenesis." (PMID 35463356, 2022). "BM-MSCs enhanced HIF-1α-dependent VEGF expression in response to the inflammatory tumor microenvironment to promote angiogenesis in colon and prostate cancers." (PMID 36230633, 2022). "This suggested that fisetin inhibited the AKT/HIF-1α signaling pathway in tumor cells by binding to AKT." (PMID 35222641, 2022). "There has been increasing evidence that high-dose irradiation per fraction markedly upregulates the expression of HIF-1α in tumors by decreasing blood perfusion and increasing tumor hypoxia." (PMID 35805044, 2022).
tumor (continued). "Tumor hypoxia is a common feature of solid malignancies, including EwS, and HIF1α along with HIF2α are primary transcription factors required for cellular adaptation to hypoxia that significantly influence metastatic potential of tumor cells." (PMID 35705030, 2022). "HIF-1α overexpression induced an increase in tumor volume in three different cell lines, and the HIF-1α-induced increase in tumor volume was abolished by knockdown of METTL4 using three different siRNA vectors." (PMID 36461076, 2022). "Neutrophil-attracting chemokines, such as CXCL1, CXCL2, or CXCL8, are induced in hypoxic tumor tissue, through the activation of hypoxia-inducible factor 1 (HIF-1α or β), and support neutrophil migration to the tumor site via CXCR1 and CXCR2 receptors." (PMID 35158807, 2022). "NIR-PMC treatment created a long-lasting hyperoxic tumour microenvironment, evidenced by a dramatic reduction in HIF-1α expression." (PMID 35918337, 2022). "HIF-1α is a critical oncoprotein that promotes tumor growth involved in angiogenesis and metastasis." (PMID 35408505, 2022). "One probable mechanism for radioresistance is the activation of the PI3K/Akt/mTOR pathway which in turn helps activate the HIF-1α-VEGF pathway in irradiated tumor cells." (PMID 36439496, 2022). "Vascular endothelial growth factor (VEGF) and hypoxia-inducible factor-1 alpha (HIF-1a) are two major players of angiogenesis in the tumor microenvironment that are upregulated by exercise in various animal models of cancer." (PMID 35945569, 2022). "There were reductions in the tumor HIF1α levels in the microbead-treated HIF1α KO mice compared with the microbead-treated WT mice." (PMID 36291563, 2022). "Another important HIF-1α mediated inflammatory response occurs via activation of nuclear factor-kappa B (NF-κB) in tumor region." (PMID 36014432, 2022). "Accumulating evidence strongly suggests that HIF-1α plays a major role in the regulation of immune cell function within the tumor microenvironment." (PMID 36578780, 2022). "This suggests that in the context of ccRCC, HIF-1α plays a tumor-suppressor role, while genetic and functional data suggest that HIF-2α and HIF-1α play opposite roles in ccRCC biology." (PMID 36364144, 2022). "IDHmut has been shown to restrict tumor aggression by decreasing HIF1α-dependent tenascin C expression, thereby decreasing ECM stiffness and mechanosignaling." (PMID 36076905, 2022). "A considerably higher proportion of ER-negative tumours, compared to ER-positive tumours, were HIF-1α positive (60% vs 25%, p < 0.0001)." (PMID 35140341, 2022). "STIM1-mediated cytosolic Ca2+ entry by the SOCE mechanism stabilizes HIF-1α via CaMKII-mediated p300 activation, thus promoting tumour proliferation." (PMID 35269437, 2022). "The serum nitric oxide metabolization dynamic was influenced by the LDH levels, Clark level, Breslow index, tumor stage, and HIF1a and HIF2a levels." (PMID 36294785, 2022). "IHC analysis of HIF-1α expression in 179 samples of 19 tumor types detected HIF-1α overexpression in 13 tumors, including LUAD." (PMID 35931669, 2022). "Expressing HIF-1α in the center of the tumor mass activates an adaptive response to hypoxia that decreases apoptosis and increases tumor cell survival, which in turn induces resistance to certain oncological treatments." (PMID 35252243, 2022). "HIF-1α promotes the transition of tumor cells from aerobic to anaerobic metabolism, increasing glycolysis to maintain energy production." (PMID 35938170, 2022). "Hypoxia-inducible factor-1α (HIF-1α) is one of the most important factors mediating the adaptive response to hypoxia in tumor tissue." (PMID 36669005, 2022). "HIF-1α is a critical transcription factor that regulates a large number of genes related to tumor progression, such as tumor growth, invasion, and metastasis." (PMID 36139362, 2022). "Minor allele carriers of the HIF1A A588T SNP had significantly reduced TMTV, a measure of tumour mass." (PMID 34708297, 2022).
tumor (continued). "For this research work, the drug delivery nanoplatform HPDA-ABS/PEG-BEZ235/Ce6 (H-APBC) in combination with phototherapy has been constructed to increase intracellular acidity, inhibit PI3K/mTOR signal and attenuate HIF-1α-dependent tumor hypoxia adaptation." (PMID 35413842, 2022). "It has been known that HIF1 is activated under hypoxic conjectures’ in tumor cells, but sometimes HIF1A activation can occur under oxygen-independent conditions." (PMID 37529254, 2022). "HIF-1α has been demonstrated the effectiveness at promoting the formation of tumor blood vessels 34 and tumor metastasis." (PMID 36439884, 2022). "The significant role of HIF-1α in tumor development has been demonstrated in various tumor types and is responsible for tumor initiation, progression, and drug resistance." (PMID 35163556, 2022). "Some reports have indicated that HIF1A upregulation is related with the invasion and metastasis of tumor cells." (PMID 36438897, 2022). "Hypoxia is known to be a characteristic feature of the tumor microenvironment, and HIF-1α is activated in the presence of both hypoxia and inflammation, which leads to the activation of vascular endothelial growth factor." (PMID 35645817, 2022). "Collectively, these data strongly implied that GSK3α regulated tumor angiogenesis via the HIF1α/VEGFA signaling pathway." (PMID 35292059, 2022). "In malignant tumors, overexpressed HIF-1α connived tumor cells to adapt to hypoxic environments, maintain nutrient acquisition, and promote further tumor growth." (PMID 36091021, 2022). "HIF-1α, as a core substance, can regulate tumor progression in several ways, and so the study of HIF-1α inhibitors becomes more and more important; we provide a brief summary for the HIF-1α inhibitors developed so far." (PMID 36139386, 2022). "According to recent literature, HBXIP drives the metabolic reprogramming of HCC through METTL3-mediated m6A methylation of HIF-1α, which stimulates the Warburg effect and tumor cell survival." (PMID 35794625, 2022). "Overall, HIF-1α is one of the key components in the adaption of tumor cells to survive under hypoxic conditions." (PMID 36140753, 2022). "In supporting this, USP7 deubiquitinates and stabilizes well-established oncogenes such as HIF-1α and N-Myc to facilitate tumor progression." (PMID 35931679, 2022). "HIF-1α was suggested to inhibit the aggressive behaviour of the tumour, while HIF-2α appeared to be the main pro-tumourigenic factor in ccRCCs." (PMID 35328822, 2022). "Activators of transcription (STAT3) mediates the signal transduction of HIF-1α to stimulate tumor growth and maintain the invasive ability of EC cells." (PMID 35800058, 2022). "This study discovers that Par can target P50 to inhibit the expression of downstream HIF-1α, a key factor in tumor glycolysis." (PMID 36260873, 2022). "The phosphorylation-activated tumorigenic signal PI3K/AKT/mTOR advances the production of downstream HIF-1α to adapt to tumor hypoxia." (PMID 35413842, 2022). "A review article showed that HIF-1α expression enhanced PC cell proliferation through multiple mechanisms by inducing neoplastic features and mediating tumorigenic crosstalk between tumor and stromal cells." (PMID 35681664, 2022). "Further supporting a hypoxic response to intrinsically promote T cell anti-tumor responses, T cells made genetically deficient in VHL or the PHD proteins that lead to proteolytic degradation of HIF-1α had increased anti-tumor activity." (PMID 35039633, 2022). "In the tumor microenvironment, deficiency of fatty acids and oxygen as well as production of IFNs upregulated viperin expression via the PI3K/AKT/mTOR/HIF-1α and JAK/STAT pathways." (PMID 36227691, 2022).